PADI2 (peptidyl arginine deiminase 2)
Diseases named in the same sentence as PADI2 in open-access papers (continued):
Sharing a sentence is not in itself a finding about the gene and the disease.
cancer (49 papers, 2012 to 2025). A tumor composed of atypical neoplastic, often pleomorphic cells that invade other tissues. "Although evidence has been steadily accumulating to indicate a significant prognostic role for PADI2 levels in patients with cancer, the pathogenic features of PADI2 in cancer are still controversial." (PMID 37627159, 2023). "Notably, dysregulation of PADI2 has also been linked to promoting the pathogenesis and progression of cancer, including breast, prostate, and colorectal cancer, and has also been suggested to promote tumor metastasis." (PMID 37627159, 2023). "Now it has been reported that targeting PADI2 in cancer is associated with phosphorylated STAT3." (PMID 32951601, 2020). "We will screen more SNPs in this region, especially in the exon region and its surrounding region, to find functional SNPs and determine how these SNPs affect PADI2 expression and the enzyme activity in which PADI2 has been implicated in some diseases and, more recently, in cancers." (PMID 27478411, 2016). "Peptidylarginine deiminase isoform 2 (PAD2/PADI2) has been implicated in cancer." (PMID 27478411, 2016). "Thus, at the molecular level, PADI2 has been implicated in EMT-mediated cancer progression." (PMID 37627159, 2023). "When normal breast cells are transformed into malignant tumors, the upregulated expression of PADI2 affects the expression of cell cycle genes, such as p21, GADD45α and Ki67, which are related to tumor progression." (PMID 37020554, 2023). "While PADI2 is overexpressed in various cancer types, and its overexpression is correlated with worse clinical outcomes, it is down-regulated in CRC, which correlates with poor prognosis." (PMID 37762371, 2023). "PADI2 has been shown to mediate the action of an anti-cancer compound that acts through the dampening Wnt signalling, while PADI4 was shown to inhibit epithelial-to-mesenchymal transition." (PMID 35706669, 2022). "This contradicts with the role of PADI2 shown in previously reported other cancer types and our results that both Padi2 knockdown and CRISPR/Cas9-mediated Padi2 knockout significantly inhibit the proliferation of osteoblasts." (PMID 35218410, 2022). "In a recent study, we found PADI2 to be highly expressed in several cancer types, notably in triple-negative breast cancer (TNBC)." (PMID 36291752, 2022). "In this context, further mechanistic and clinical studies will reveal how using PADI2 based screening assays will improve cancer treatment strategies." (PMID 32079300, 2020). "Our previous results showed that the expression of PADI2 was significantly increased in immunohistochemistry of a variety of cancers, including serous ovarian papillary adenocarcinoma, compared to normal tissues." (PMID 32951601, 2020). "In contrast to these cancers, PADI2 levels can be downregulated in colorectal cancer (CRC) patients." (PMID 32079300, 2020). "Further, PADI2 overexpression can occur in multiple cancers, including breast ductal carcinoma, ovarian serous papillary adenocarcinoma, cervical squamous cell carcinoma, liver hepatocellular carcinoma, lung cancer, and also papillary thyroid carcinoma." (PMID 32079300, 2020). "In this review, we focus on the role of PADI2-mediated arginine citrullination and their functional impact on transcriptional regulation and cancer progression." (PMID 32079300, 2020). "While this is interesting, and perhaps suggests the expression of a different PADI family member in this basal cell line, we have focused on PADI2 expressing cancers for this study, which are predominantly luminal and HER2/ERBB2 expressing." (PMID 23110523, 2012). "Notably, PADI2 has been considered to play an essential role in the metastasis and development of cancer." (PMID 37627159, 2023). "It is also unknown whether PADI2 is a significant risk factor causing BTC progression and impacts survival in cancer patients." (PMID 37627159, 2023).
cancer (continued). "Importantly, the authors show that PADI2 inhibition restores chemosensitivity in resistant cancer cells." (PMID 37778381, 2023). "To mention only a few, we have observed different expression of the CTCFL gene—oncogene—which is tested as a target gene in the immunotherapy of cancer, PADI2—a novel angiogenesis-regulating gene, or USP53—which is a novel molecular biomarker for weight control." (PMID 31756991, 2019). "Our current study suggests that PADI2 may also play a role in cancer progression, and this prediction is supported by several previous studies." (PMID 23110523, 2012). "Therefore, it may be speculated that the increased PADI2 expression levels in A549 cells may lead to alterations in these cancer cells in order to promote cell survival and pathogenesis." (PMID 32629995, 2020). "These two studies therefore describe anti-tumorigenic functions of PADI2 and PADI4, through dampening of cancer promoting signal transduction pathways." (PMID 35706669, 2022). "The PADI family consists of five members, with PADI2 and PADI4 being predominantly expressed in cancer." (PMID 36291752, 2022). "The mRNA expression level of PADI2 and PADI4 was lower in cancer cell lines, compared to GES1 control cells, by q-RT-PCR, though PADI4 protein levels were higher in SGC7901 and MKN45 cells." (PMID 31058095, 2019). "In prolactinomas and growing prolactinomas, PADI2 and PADI4 can promote the upregulation of the HMGA1, N-MYC and IGF-1 oncogenes by catalyzing the citrullination of histones, thus promoting the proliferation of cancer cells." (PMID 37020554, 2023). "Given the fact that PADI2 and 4 are the most expressed in humans, therefore most of the studies had focused on understanding their functions and other members of the PADI family have not been studied in the context of their implications in the specific type of cancer progression." (PMID 32079300, 2020). "However, how PADI2 influences gene expression in cancer cells is not fully understood." (PMID 32079300, 2020).
tumor (42 papers, 2012 to 2025). "The authors suggested that loss of nuclear PADI2 expression may therefore represent a marker of progression towards more aggressive neoplasia." (PMID 27478411, 2016). "We aimed to determine whether these common polymorphisms in the PADI2 region are associated with various tumor risks using the Sequenom MassARRAY genotyping method." (PMID 27478411, 2016). "The further analysis of the H-score in different regions of the tumor and control tissues showed significant differences in PADI2 (p < 0.0001), citENO1 (p < 0.0001), and ENO1 (p = 0.0016)." (PMID 40573960, 2025). "As a control, we analyzed the mammary fat pad of non-tumor-bearing mice, which showed the low expression of PADI2 and citENO1 and the moderate expression of ENO1." (PMID 40573960, 2025). "In a distinct study, Zheng and colleagues provided persuasive findings showing that PADI2 plays a crucial role in promoting angiogenesis, cellular growth, movement, and influencing the tumor immune environment." (PMID 39278916, 2024). "PADI2 can also participate in the migration and invasion of tumor cells by mediating the transmission of some signaling pathways." (PMID 37020554, 2023). "PADI2 expression is reported to be increased in many types of tumor tissues including breast, cervical, esophageal, colon, lung, gastric, liver, and etc.." (PMID 35218410, 2022). "The expression of PADI2 in regulation of tumorigenesis seems to be cell‐type and tumor microenvironment‐dependent." (PMID 33747724, 2021). "McElwee reported that overexpression of PADI2 in mice led to occur EMT in tumor cells, which decreased E-Cadherin expression and increased Snail and Vimentin expression." (PMID 32951601, 2020). "Based on the genotyping result, we focused on analyzing the tumorigenic role of PADI2 in cultured tumor cells." (PMID 27478411, 2016). "RNA interference with PADI2 expression resulted in significant alteration of the expression of some genes involved in tumor progress and signal transduction." (PMID 27478411, 2016). "The tumorigenic pathway of PADI2 was analyzed in the MCF-7 tumor cell line using tumorigenesis-related PCR arrays." (PMID 27478411, 2016). "The Sequenom MassARRAY and TaqMan genotyping methods were used to investigate the correlation between PADI2 gene SNPs and various tumor risks." (PMID 27478411, 2016). "In order to investigate PADI2 expression during tumor progression, we first utilized TaqMan quantitative real-time PCR (qRT-PCR) to measure PADI2 mRNA levels in cells from the MCF10AT tumor progression series." (PMID 23110523, 2012). "PADI2 can participate in tumor cell migration and invasion by regulating gene expression." (PMID 37020554, 2023). "Thus, PADI2 represents a multifaceted protein that not only involves tumor progression but also affects tumor immunity." (PMID 37627159, 2023). "However, because PADI2 can participate in tumor progression by mediating tumor proliferation, migration and invasion, tumor angiogenesis and drug resistance, it has become an important target in tumor treatment." (PMID 37020554, 2023). "The present study demonstrated that PADI2 proteins were substantially highly expressed in BTC tumor tissues, and PADI2 could be an independent prognostic biomarker for predicting clinical outcomes in BTC patients." (PMID 37627159, 2023). "PADI2 is also involved in tumor cell migration and invasion by mediating EVs." (PMID 37020554, 2023). "First, PADI2 can affect the proliferation of tumor cells by regulating gene expression." (PMID 37020554, 2023). "Second, PADI2 can mediate the migration and invasion of tumor cells." (PMID 37020554, 2023). "However, some evidence also exists to suggest that PADI2 over-expression can act as a tumour initiating mechanism." (PMID 35706669, 2022). "The inhibition of PADI2 expression was confirmed in the cultured tumor cells using real-time PCR." (PMID 27478411, 2016).
tumor (continued). "The actual mechanisms by which Cl-amidine reduces cellular proliferation have yet to be fully elucidated, though evidence here suggests that PADI2 may play a role (direct or indirect) in regulating the expression of both cell cycle and tumor promoting genes." (PMID 23110523, 2012). "This study revealed that the PADI2/MEK1/ERK/IGF2BP1 pathway could promote the characteristics of carcinogenic tumor cells in EC, and the combination of specific PADI2 and MEK1 inhibitors might provide a novel therapeutic target site for the treatment of the MEK inhibitor-resistant EC patients." (PMID 36371254, 2022). "PADI2 is capable of citrullinating the nuclear antigen Nucleophosmin at position 277, a modification that can be targeted by CD4 T cells for anti‐tumour therapy." (PMID 40078091, 2025). "The overexpression of PADI2 can upregulate the expression of ACSL4 and BIRC3, downregulate the expression of CA9, promote abnormal lipid metabolism and tumor cell invasion, and lead to the abnormal migration of breast tumor cells." (PMID 37020554, 2023). "Studies have shown that PADI2, PADI3 and PADI4 in the PADI family promote the carcinogenic microenvironment by mediating the formation of EVs, leading to tumor invasion." (PMID 37020554, 2023). "A study by the same laboratory showed that MEK1 is targeted by PADI2 in endometrial cancer and the citrullination event promotes MEK1-mediated phosphorylation of ERK1/2, facilitating tumour progression." (PMID 35706669, 2022). "It was found that cells that overexpressed PADI2 in vitro were more tumorigenic and elevated inflammation and EMT markers, which promoted tumor progression." (PMID 32951601, 2020). "Our study highlighted, for the first time, a considerable correlation between the high PADI2 expression on IHC stains and unfavorable prognosis in BTC, which may be clinically applied to predict tumor control and patients’ survival." (PMID 37627159, 2023). "ST1926 treatment down-regulated a group of oncogenic proteins (SLC2A1, SLC25A6, CBX3, DEK, DDX39B) and up-regulated a group of presumably tumor-suppressing proteins (PEBP1, HspBP1); PADI2 and CMPK1, of unknown function in GBM, were also up-regulated." (PMID 37762371, 2023). "High expression of PADI2 and PADI3 can reduce the expression of moesin, increase extracellular vesicles (EVs) to release tumor-promoting factors, reduce EV tumor suppressors, and increase the invasiveness of tumor cells, thereby promoting the malignant progression of PDAC." (PMID 37020554, 2023). "We observed that the staining of PADI2 was in the cytoplasm and nuclei of BTC tumor cells." (PMID 37627159, 2023). "We found that PADI2 expression was upregulated in tumor tissues compared with nontumor tissues." (PMID 32951601, 2020).
infection (17 papers, 2014 to 2025). The state of being infected such as from the introduction of a foreign agent such as serum, vaccine, antigenic substance or organism. "After 24 h of continuous infection, we detected the expression of PADI2 and macrophage polarization marker genes." (PMID 41146353, 2025). "In summary, through RNA-seq analysis, we demonstrated that sheep MO infection induces an increase in PADI2 expression in alveolar macrophages." (PMID 41146353, 2025). "The role of PADI2, a central enzyme in protein citrullination, has garnered increasing attention for its role in inflammatory diseases and infection immunity." (PMID 41146353, 2025). "Immunohistofluorescence (IHF) staining revealed a significant increase in the number of macrophages, which were widely distributed in the alveolar cavity, in the MO infection group, and PADI2 was also positively expressed in the macrophages." (PMID 41146353, 2025). "In this study, we performed RNA-seq on the BALF of sheep infected with MO and reported that PADI2 expression significantly increased after MO infection." (PMID 41146353, 2025). "To determine the changes in the expression of PADI2 after the MO infection of macrophages, we isolated BMDMs in vitro and infected them with MO for 24 h." (PMID 41146353, 2025). "In this study, the expression of PADI2 increased in the BMDMs after infection." (PMID 41146353, 2025). "In systemic infection, PADI2 and PADI4 can lead to the deterioration of infection by promoting NETosis, and PADI2 can also lead to the deterioration of infection by inducing cell apoptosis." (PMID 37020554, 2023). "qPCR analyses of BALF cell lysates demonstrates that there was a notable elevation in Nlrp3 gene expression after PA infection, which was substantially reduced in DKO mice compared with WT counterparts, suggesting a regulatory effect of PADI2 and PADI4 on Nlrp3 expression." (PMID 39405117, 2024). "Infection of 16HBE14°− cells with HRV did not significantly alter mRNA levels of either PADI2 or PADI4." (PMID 32117246, 2020).
neurodegenerative disease (9 papers, 2021 to 2024). A disorder of the central nervous system characterized by gradual and progressive loss of neural tissue and neurologic function. "In neurodegenerative diseases, the high expression of PADI2 leads to the abnormal accumulation of citrullinated proteins and promotes their malignant progression, while PADI4 can lead to inflammation through citrullinated histone H3, thus promoting the progression of neurodegenerative diseases." (PMID 37020554, 2023). "It has been addressed in other neurodegenerative diseases like schizophrenia; however, it has not presented meaningful results associated with PADI2." (PMID 38132149, 2023). "However, PADI2, PADI3 and PADI4 can also inhibit the progression of neurodegenerative diseases by participating in the differentiation, apoptosis and senescence of nerve cells." (PMID 37020554, 2023).
adenocarcinoma (1 paper, 2020). A common cancer characterized by the presence of malignant glandular cells. "In vitro lung epithelial and adenocarcinoma alveolar cell models revealed that PADI1, PADI2 and PADI4 mRNA levels were elevated, but PADI3 and PADI6 mRNA levels were reduced in SARS-CoV-2-infected NHBE cells." (PMID 32629995, 2020).
inflammation (1 paper, 2025). Aberrant reaction of the microcirculation characterized by movement of fluid and leukocytes from the blood into extravascular tissues. "It is known that enzymes PADI2- and PADI4-dependent citrullination of LL-37 occurs in the human lung, and that PADI4 activation increases in IL-17-driven neutrophilic airway inflammation." (PMID 40410820, 2025).
neurologic diseases (1 paper, 2022). "In this study, we sought to define the cellular and regional expression of the gene encoding for PAD2 (i.e. PADI2) in the CNS and evaluate whether anti-PAD2 antibodies were present in patients with MS and other neurologic diseases with known or suspected autoimmune etiology." (PMID 35734473, 2022). "In this study, we sought to define the cellular and regional expression of the gene encoding for PAD2 (i.e. PADI2) in the human CNS using publicly available datasets and evaluate whether anti-PAD2 antibodies were present in patients with various neurologic diseases." (PMID 35734473, 2022).
PADI2 also shares sentences with these, for which no sentence is quoted: bacterial infection (5 papers); Parkinson disease (5); Hepatic fibrosis (3); lung disease (3); prion disease (3); astrocytomas (2); breast (2); cervical carcinoma (2); colitis (2); diabetes (2); leukemia (2); open-angle glaucoma (2); pancreatic cancer (2); septic shock (2); X-linked dystonia-parkinsonism (2); acute myeloid leukemia (1); acute respiratory distress syndrome (1); ankylosing spondylitis (1); ankylosis (1); autoimmune hepatitis (1); bacteremia (1); brain cancer (1); carcinomas of kidney (1); cardiovascular disease (1); cervical squamous cell carcinoma (1); chronic obstructive pulmonary disease (1); co-infection (1); coagulopathy (1); colon adenocarcinoma (1); digestive system cancer (1).
A further 35 diseases each share a sentence with PADI2 in 1 paper.